S100A9 (S100 calcium binding protein A9)
Diseases named in the same sentence as S100A9 in open-access papers (continued):
Sharing a sentence is not in itself a finding about the gene and the disease.
cervical cancer (13 papers, 2013 to 2024). A primary or metastatic malignant neoplasm involving the cervix. "We also analyzed the expression of TXNDC12, CD31 (neovascularization marker gene), and S100A9 (neutrophil marker gene) by IHC experiments in cervical cancer tissues." (PMID 36712973, 2022). "Consistent with the acetylome results, CREBBP and S100A9 were up-acetylated in cervical cancer tissues compared with adjacent normal tissues." (PMID 32489318, 2020). "Furthermore, the acetylated levels of CREBBP and S100A9 in cervical cancer tissues were confirmed by immunoprecipitation (IP) and Western blot analysis." (PMID 32489318, 2020). "For instance, S100A9 inhibits human cervical cancer cell metastasis." (PMID 26431492, 2015). "There are many subtypes of S100 calcium-binding protein, and several studies have found that S100A7, S100A9, S100A11, and S100A14 are closely related to cervical cancer." (PMID 36230965, 2022). "S100A9 promoted cell proliferation and migration through activating the EMT and Wnt/β-catenin pathway in cervical cancer." (PMID 34249502, 2021). "ST analysis depicted the spatial overlap of IFIT1 and neutrophil biomarkers S100A9, and PDL1 on Cervical cancer (CESC), Glioblastoma Multiforme (GBM), Renal cell carcinoma (RCC), Breast invasive carcinoma (BRCA), and Bladder urothelial carcinoma (BLCA) cancer tissues." (PMID 38898490, 2024). "They found that S100A9, eEF1A1, PKM2, COPA and so on, may become candidate markers for early diagnosis of cervical cancer and new targets for therapy." (PMID 36498728, 2022).
lung adenocarcinoma (13 papers, 2015 to 2025). A carcinoma that arises from the lung and is characterized by the presence of malignant glandular epithelial cells. "The percentage of blood S100A9+ MDSC in the EGFR-mutated lung adenocarcinoma patients (17.7 ± 10.6, n = 58) was higher than that of healthy donors (7.5 ± 1.8, n = 7, p = 0.008)." (PMID 29484139, 2018). "In lung adenocarcinoma, tumor-associated macrophage (TAM) infiltration significantly increases, causing the release of S100A9, which binds to the RAGE receptor on the surface of lung adenocarcinoma cells, and then activates the NF-κB pathway to promote EMT." (PMID 41155408, 2025). "The Overall Survival analysis performed by using the Kaplan Meier method on lung adenocarcinoma patients retrieved from TCGA revealed that a higher expression of S100A9 significantly correlates with a poor clinical outcome." (PMID 35116033, 2021). "According to The Cancer Genome Atlas lung adenocarcinoma (TCGA-LUAD) data, we found that multiple LSLC markers such as S100A9, HSPA6, and FAM83A were associated with a poor prognosis in lung adenocarcinoma patients." (PMID 34127680, 2021). "Twenty different tumor tissue samples from patients with lung adenocarcinoma, were analyzed by immunohistochemistry (IHC) for the expression of S100A9, a suitable marker for PMN-MDSC identification." (PMID 35116033, 2021). "S100A9 was shown to attract monocyte infiltration into lung adenocarcinoma and enhanced the expression of myeloid markers in S100A9-bearing tumor tissues." (PMID 26315114, 2015). "Targeting TAMs and their specific secreted factors, such as CXCL7 in CRC and S100A9 in lung adenocarcinoma, could therefore offer a strategy to intervene in resistance mechanisms tailored to different tumor types." (PMID 40368902, 2025). "Similar to the lung adenocarcinoma model, s100a9 loss of function did not generate any phenotype in vivo before treatment." (PMID 35411077, 2022). "In this report, we correlated S100A9+ MDSCs and TAMs to EGFR-TKI treatment response in patients with EGFR mutated lung adenocarcinoma and addressed the question as to whether this MDSC is a source of TAMs." (PMID 29484139, 2018). "In the study, we showed the clinical relevance of S100A9+ MDSCs and TAMs in terms of microenvironment-mediated resistance to EGFR-TKIs in the setting of lung adenocarcinoma harboring activating EGFR mutations and linked the circulating S100A9+ MDSCs to tumor microenvironment." (PMID 29484139, 2018). "It binds with the S100A9 protein in the cytoplasm, activating the MAPK pathway and plays a positive role in the progression and metastasis of lung adenocarcinoma cells." (PMID 40491847, 2025). "In addition, in vivo, and in vitro experiments have shown that the target gene S100A9 of LINC00852 has a positive regulatory effect on the growth, migration, invasion, and metastasis of lung adenocarcinoma cells." (PMID 36465402, 2022). "S100A9 strongly activates P38 and Rek1/2 kinases and slightly activates JNK kinase phosphorylation in the MAPK pathway in A549 (human alveolar basal epithelial cells) and SPCA-1 cells, thereby promoting the progression and oncogenic ability of SM in lung adenocarcinoma." (PMID 36465402, 2022).
multiple myeloma (13 papers, 2019 to 2025). "Our results showed that myeloma-associated macrophages also expressed S100A9, which is affected by neutrophil depletion in lymph nodes." (PMID 34150664, 2021). "Thus, the higher level of S100A8/S100A9 in the BM of multiple myeloma–bearing mice was associated the accumulation of MDSC in the presence of tumor cells and increased production of S100A8/S100A9 by these MDSC." (PMID 36923707, 2023). "Given the importance of TLR signaling for myeloma cells, it is unknown why the association of S100A9 with TLR activation, particularly their effects on the tumor cell fate, in myelomagenesis remains unexplored." (PMID 34150664, 2021). "Interestingly, our finding suggested the involvement of the proteasome inhibitor-Bortezomib in both canonical NF-κB and MAPK/p38 signaling pathways, highlighting TNFRSF13B as a big player in S100A9-associated myeloma progression." (PMID 34150664, 2021). "Our work provided first evidence that S100A8/S100A9 proteins are at least partially responsible for the supporting megakaryopoiesis in the myeloma BM." (PMID 36923707, 2023). "Tumor-free and DP42 multiple myeloma–bearing S100A9 KO mice displayed significantly lower numbers of MKs than their WT counterparts." (PMID 36923707, 2023). "Blockade of S100A9 with TQ had a potent antitumor effect and markedly potentiated the effects of several commonly used anti-multiple myeloma therapeutics in several multiple myeloma mouse models." (PMID 36923707, 2023). "Our results demonstrated a novel mechanism by which S100A8/S100A9 can regulate BM TME in multiple myeloma via upregulation of MKs." (PMID 36923707, 2023). "Here, we describe a novel mechanism by which S100A8/S100A9 proteins produced by BM neutrophils and monocytes promote the expansion of megakaryocytes supporting multiple myeloma progression." (PMID 36923707, 2023). "Tasquinimod, an inhibitor of S100A9, is currently in a phase Ib/IIa clinical trial in multiple myeloma patients (NCT04405167)." (PMID 37138869, 2023). "To investigate the involvement of S100A8/S100A9 in multiple myeloma progression, we evaluated the amount of these proteins in the BM of tumor-free and DP42 myeloma-bearing mice." (PMID 36923707, 2023). "An increased number of BM CD11b+Gr1+ cells (MDSC) as well as increased production of S100A8/S100A9 by these cells contributed to the elevated levels of S100A8/S100A9 proteins in multiple myeloma–bearing hosts." (PMID 36923707, 2023). "Our study fosters the evaluation of the S100A9 inhibitor tasquinimod, already in clinical trial for the treatment of relapsed/refractory multiple myeloma patients, in AML, as a single agent or in combination with venetoclax." (PMID 38110349, 2023). "The levels of S100A8/S100A9 in the BM of patient with multiple myeloma were significantly elevated when compared with those in peripheral blood of these patients as well as to the S100A8/S100A9 levels reported in healthy donors." (PMID 36923707, 2023). "Our study demonstrated a significant role of the myeloid-derived proteins S100A8/S100A9 in the progression of multiple myeloma." (PMID 36923707, 2023). "To determine a possible biological role of S100A8/S100A9 in multiple myeloma, we assessed the therapeutic effect of TQ in different models of multiple myeloma." (PMID 36923707, 2023). "Specifically, we discovered a novel role of S100A8/S100A9, the most abundant proteins produced by neutrophils and monocytes, in regulation of myeloma progression via promotion of the megakaryocyte expansion and angiogenesis." (PMID 36923707, 2023). "Myeloid-derived S100A9 enhanced survival signals delivered by TNFSF13B receptors for myeloma cell survival and progression, resulting in shorter survival of MM patients within 3 years from diagnosis." (PMID 34150664, 2021). "The authors confirmed the ability of S100A9 to induce the secretion by myeloid-derived suppressor cell (MDSCs) of inflammatory and pro-myeloma cytokines including TNFα, IL-6, and IL-10." (PMID 34445745, 2021).
multiple myeloma (continued). "Specifically, TNFSF13B expression had close interactions with macrophage marker genes, namely, TLR and S100A9 genes; their receptor genes, TNFRSF13B and TNFRSF17, showed significant associations with the myeloma-related genes CD38, SDC1, and MYEOV." (PMID 34150664, 2021). "Based on correlation analysis of integrated scRNA-seq and bulk RNA-seq datasets from patients, we confirmed that myeloid-derived S100A9 was involved in TNFSF13B-dependent myeloma cell proliferation and survival." (PMID 34150664, 2021). "As a result, the increased amount of S100A8/S100A9 in multiple myeloma BM was not sufficient to cause a detectable effect on myeloid cells." (PMID 36923707, 2023). "We assessed the role of S100A8/S100A9 proteins in BM angiogenesis in the model of multiple myeloma." (PMID 36923707, 2023). "Next, we evaluated the presence of S100A8/S100A9 protein in patients with multiple myeloma." (PMID 36923707, 2023). "We found the correlation of myeloid-derived S100A9 with TNFSF13B dependency in myeloma cells." (PMID 34150664, 2021). "However, more studies are needed to better understand a clinical significance of S100A8/S100A9 within the established multiple myeloma—myeloid–MK axis that may regulate megakaryopoiesis in patients with multiple myeloma." (PMID 36923707, 2023). "S100A9 induced MDSC to express and secrete inflammatory and pro-multiple myeloma cytokines, including TNFα, IL6, and IL10." (PMID 36923707, 2023). "Our results demonstrated that S100A9 administration upregulated TNFRSF13B and TNFRSF17 surface expressions on myeloma cells, indicating crosstalk between TLR activation and TNFSF13B signaling." (PMID 34150664, 2021). "Another study reported that S100A9, produced by MDSC, can promote the angiogenesis and metastasis of multiple myeloma." (PMID 34689842, 2021). "In the animal experiments, we proved that S100A9 was required for both TNFSF13B production by myeloid cells and myeloma cell survival." (PMID 34150664, 2021). "Human CD34+ hematopoietic progenitor cells were isolated from the BM of patients with multiple myeloma and differentiated to MKs with or without S100A9." (PMID 36923707, 2023). "In conclusion, myeloid-derived S100A9 can enhance TNFSF13B/TNFRSF13B expression on myeloma cells, stimulating both canonical and non-canonical NF-κB pathways and thereby fuels tumor cell proliferation." (PMID 34150664, 2021). "This protection may be attributed to enhanced TNFSF13B signal transduction via S100A9/TLR binding, which has been proven to be critical for myeloma growth." (PMID 34150664, 2021). "The effect of S100A9 was specific to MKs, as S100A9 did not affect the expression of cytokines by stroma cells generated from the BM of tumor-free mice or upregulate expression of Vegf in multiple myeloma cells." (PMID 36923707, 2023). "Cells of BM TME did not induce S100A9 production by multiple myeloma cells." (PMID 36923707, 2023). "We hypothesized that S100A8/S100A9 may have a particularly important role in multiple myeloma growth given the abundance of MDSC in the myeloma BM TME and that TQ would therefore be effective at inhibiting multiple myeloma progression." (PMID 36923707, 2023). "MDSC production of S100A9, a calcium-binding protein that promotes the release of TNF-α, IL-6, and IL-10 in autocrine pathway through TLR4 interaction, attracts myeloma cells in the TME and supports myeloma cell growth via the activation of the canonical NFκB pathway." (PMID 36726975, 2022). "In addition to the increased number, CD11b+Gr-1+ cells from the BM of multiple myeloma–bearing mice produced higher amounts of S100A9 protein, which is consistent with the accumulation of MDSC in tumor-bearing mice because MDSC are known to express more S100A9 protein than neutrophils and monocytes." (PMID 36923707, 2023).
multiple myeloma (continued). "In addition to blocking S100A9, TQ has been previously reported to bind HDAC4 and inhibit its activity; this could be an additional mechanism by which treatment with TQ delayed multiple myeloma progression." (PMID 36923707, 2023).
viral infection (13 papers, 2010 to 2024). "In summary, we have identified extracellular S100A9 as a host-derived molecular pattern that regulates inflammation during virus infection." (PMID 24391503, 2014). "4-OH-TAM also down-regulated a number of genes, including PGR, S100A8, S100A9, CCND1 and ANEXA1, which are involved in IFN α/β signaling pathway and immune/inflammatory response to viral infection." (PMID 29416786, 2018). "However, during viral infection, the expression of ISGs including DHX58, IFITM3, ISG15, and OASL was upregulated in the livers of WT mice, while Neurl3−/− livers expressed a higher level of proteins related to inflammatory response such as S100A9 and CD47." (PMID 35792897, 2022). "In addition, there has been no report of DAMP proteins like S100A9 activating PRR signaling during virus infection." (PMID 24391503, 2014).
bladder cancer (11 papers, 2010 to 2025). "An overexpression of S100A9 is associated with stage progression, invasion, metastasis, and poor survival in bladder cancer patients." (PMID 38254738, 2024). "By contrast, expression of S100A8/S100A9 in sera has been reported to be associated with recurrence-free survival with bladder cancer." (PMID 34650982, 2021). "Studies have investigated the role of S100A9 in tumorigenesis; however, the underlying molecular mechanism(s) in bladder cancer remains unknown." (PMID 34885040, 2021). "In summary, using a series of bioinformatics and retrospective analyses, the present study identified a subset of seven genes (CDC20, CDKN2A, CTSV, FOXM1, KRT23, MAGEA6, and S100A9), which were significantly associated with progression and prognosis of bladder cancer." (PMID 34885040, 2021). "Further validation using quantitative real-time PCR in various bladder cancer cell lines confirmed the elevated expression of S100A9, particularly in those representing advanced disease stages." (PMID 41009692, 2025). "Particularly, S100A9 has been shown to be highly expressed in bladder cancer tissues in large-scale clinical studies, and its expression levels are also elevated in the urine of patients." (PMID 37691944, 2023). "Expression of S100A9 was downregulated in all bladder cancer cells, compared to Urosta 0.16, 2.12, 1.45, and 0.13-fold downregulation in RT4, J82, HT1197, and 253JB-V cells at p-value 0.000." (PMID 34885040, 2021). "The PPI network analysis of three databases identified the following subsets of DEGs, including CDC20, CDKN2A, CTSV, FOXM1, KRT23, MAGEA6, and S100A9, which were significantly upregulated in bladder cancer." (PMID 34885040, 2021). "The expression profile of CDC20, CDKN2A, CTSV, FOXM1, KRT23, MAGEA6, and S100A9 were significantly higher in bladder cancer specimens compared with normal bladder tissue in patients." (PMID 34885040, 2021). "Normal human bladder tissue is known to express both S100A9 and lipocalin-2; in bladder cancer, expression of both increases." (PMID 25354343, 2014). "In this review, we focus on describing the emerging evidence for GDF15, VEGF, TGF-β1, HSP90, HMGB1, and S100A9 as candidate biomarkers across renal and bladder cancers—highlighting their biological rationales, analytical performance characteristics, and prospective roles in clinical practice." (PMID 41009692, 2025). "Additionally, we explored the impact of the S100A9 gene on bladder cancer cells in cell lines, thereby advancing research in this field." (PMID 37691944, 2023). "Moreover, S100A9 overexpression can lead to resistance to cisplatin-induced apoptosis in bladder cancer, whereas S100A9 inhibition can enhance tumor cell sensitization to cisplatin-induced apoptosis." (PMID 37701037, 2023). "A total of seven genes, including CDKN2A, CDC20, CTSV, FOXM1, MAGEA6, KRT23, and S100A9 were confirmed with strong prognostic values in bladder cancer and validated by qRT-PCR conducted in various human bladder cancer cells representing stage-specific disease progression." (PMID 34885040, 2021). "To further understand the association between MAGEA3 and MAGEA6 with S100A9, we explored the OncoDB cancer database, a large-scale multi-omics database, and performed pairwise gene expression correlation analysis between MAGEA3 and MAGEA6 and S100A9 in bladder cancer patients." (PMID 38254738, 2024). "Firstly, fluid-based measurements—notably urinary HMGB1 and urinary VEGF in bladder cancer and serum or tissue assessments of GDF15, HSP90, and S100A9 in renal tumors—provide viable, minimally invasive opportunities to complement imaging and histopathology." (PMID 41009692, 2025). "In existing research, several genes have been identified to have an impact on the prognosis of bladder cancer, such as SERPINE2, SNCAIP, S100A9, and others." (PMID 37691944, 2023).
bladder cancer (continued). "Through integrated bioinformatics analyses of multiple gene expression datasets, S100A9 emerged among seven key genes differentially expressed between non-muscle-invasive and muscle-invasive bladder cancer specimens." (PMID 41009692, 2025). "Higher expression levels of S100A9 were observed in muscle-invasive bladder cancer tissues compared to non-muscle-invasive forms, indicating its role in tumor advancement." (PMID 41009692, 2025).
glioblastoma (11 papers, 2014 to 2025). The most malignant astrocytic tumor (WHO grade IV). "Our results revealed 3 candidate biomarkers useful in glioblastoma diagnostic: CXCL4, S100A8 and S100A9, with increased serum levels/tissue overexpression in glioblastoma versus control." (PMID 25298751, 2014). "Further studies have corroborated the presence of increased S100A8 and S100A9 levels in glioblastoma." (PMID 34975408, 2021). "S100A9 from glioblastoma subjects had an average value of 277.72 pg/mL, almost twice the average value of controls (124.25 pg/mL)." (PMID 25298751, 2014). "Although this signaling pathway was previously reported to be involved in radioresistance of glioblastoma and other contexts, it has not been linked to S100A9 or therapeutic resistance in brain metastasis." (PMID 35411077, 2022). "The S100A8/S100A9 subtypes may be promising biomarkers for glioblastoma." (PMID 34975408, 2021). "Markers of innate immunity including CD68, S100A9, HLADR, NLPR3, interleukin (IL) 1β, IL-6, TNFα and NF-κB were significantly increased in human derived glioblastoma samples compared to healthy control brain." (PMID 41034696, 2025). "Using SELDI-ToF MS technology, a set of potential serum biomarkers for glioblastoma diagnostic was assessed, finding three proteins, chemokine CXCL4, as well as S100A8 and S100A9 proteins as putative GBM biomarkers, whose serum levels in glioblastoma were increased in comparison with controls." (PMID 32456359, 2020). "However, despite showing greater expression, serum levels of S100A9 were not a sufficient prognostic measure of glioblastoma at higher transcript levels, while only S100A8 maintained a significant correlation as a marker." (PMID 34975408, 2021).